IL15 (interleukin 15)
Diseases named in the same sentence as IL15 in open-access papers (continued):
Sharing a sentence is not in itself a finding about the gene and the disease.
cancer (continued). "Next, we boosted immunizations with IL-15:IL-15Rα-B16F10-OVA with the same doses 2 weeks after the priming injection to analyze whether the boosting immunization would protect against future exposure to live cancer cell injection in mice." (PMID 34439192, 2021). "In this study, we engineered a BacMam virus (BV) to carry either the self-assembling IL-15 or the IL-15Rα gene and evaluated whether immunization with a BacMam-based IL-15:IL-15Rα complex-expressing cell-based cancer vaccine could provide anticancer protection in mice." (PMID 34439192, 2021). "Thus, IL-15 appears to enhance the therapeutic effect of cancer-targeted NIR-PIT." (PMID 34200194, 2021). "Furthermore, we could show that the enhanced cytotoxicity of IL-2/IL-15-expanded cells extended to other cancer cell lines, also of different origin." (PMID 32983105, 2020). "Furthermore, IL‐15 or pharmacologically enhanced IL‐15 superagonists like N‐803 are the subject of clinical trials with more than 50 ongoing studies of cancer of which at least four specifically focus on PDAC (NCT03329248, NCT03387098, NCT03586869 and NCT03136406)." (PMID 32821382, 2020). "IL-15 might have potential to become a versatile adjuvant after cancer NIR-PIT." (PMID 32927646, 2020). "Understanding the multifaceted nature of IL-15 remains worthy of further exploration, as comprehending the roles of IL-15sol vs IL-15Rc and the dynamic interplay between them may ultimately provide novel cancer treatments." (PMID 31856922, 2019). "The modifying effect of immune-related conditions on the IL-15 association persisted in analyses allowing for independent effect modification by lag-time interval before cancer diagnosis or age at cancer diagnosis, but neither effect modification by lag-time nor age remained significant." (PMID 30297770, 2018). "Due to the pleiotropic attribute of IL-15 to stimulate both the innate and the adaptive arm of the immune system and growing preclinical data on IL-15-mediated antitumor immunity, IL-15 was categorized as one of the immunotherapeutic agents with high potential for broad usage in cancer therapy." (PMID 28785596, 2017). "However, whether IL-15 is required for the development or suppression of inflammation-induced cancer is poorly understood." (PMID 29255466, 2017). "This suggests that IL-15 treatment could promote death of cancer cells." (PMID 28379958, 2017). "However, it remains to be investigated whether and how IL-15 might enhance cancer-promoting inflammation." (PMID 29255466, 2017). "Also, it has been reported that IL-15 treatment of RCC CD105+CSCs could suppress cancer progression." (PMID 27588469, 2016). "Thus we hypothesized that the IL-12-adjuvanted cell vaccine might induce IL-15, which in turn might have a role in cancer immunoprevention." (PMID 25997501, 2015). "Additionally, the reduced effect of the IL15 could be explained by recent elucidation of IL15 in cancer therapy." (PMID 24369443, 2013). "Additionally, IL15 activates neutrophils and dendritic cells and generates cytotoxic T lymphocytes against cancer cells, so the blocking of the IL15 signalling pathway weakens the immune system's ability to resist cancers." (PMID 24555436, 2013). "A novel feature of TAB16 is its dual functionality, as it synergizes with IL-15 to enhance NK cell activation and proliferation and targets ADAM17 overexpressed on cancer cells to induce ADCC." (PMID 41694365, 2026). "Compared to IL‐2 or IL‐15, CAR‐T cells that secrete IL‐23 not only demonstrate superior anti‐cancer functionality but also offer unique safety advantages due to the specific mechanism of IL‐23 production." (PMID 40395752, 2025). "In the presence of IL-15, IFN-γ production significantly increased in coculture with cancer cells compared to monoculture alone (p < 0.0001) and was unaffected by ribociclib treatment in both monoculture and coculture conditions." (PMID 40032842, 2025).
cancer (continued). "IL‐2 or IL‐15 can significantly enhance the proliferation of CAR‐T cells in tumors thereby prolonging their survival and anti‐cancer function in vivo." (PMID 40395752, 2025). "Additionally, the production of IL-15 is highly correlated with exercise, suggesting that interventions in lifestyle habits (such as physical activity) during the early stages of cancer may influence the overall cancer outcomes." (PMID 39911393, 2025). "Exogenous IL-15 improves CDK4/6 inhibitor efficacy by augmenting T-cell proliferation and cancer cell killing by T cells." (PMID 40032842, 2025). "Cancer cells modulate the expression and secretion of several anti-proliferative molecules on DBMSCs, including, CD40LG, CXCL9, IL9R, IL-15, TNFSF13B, IL-9, IL-17, and CXCL1." (PMID 39768220, 2024). "Thus, the observation made in healthy individuals of enhanced IL-15 levels for 10-120 min after acute exercise 91, allowed to establish that the better prognosis reported in regularly training cancer patients may originate from up-regulation of IL-15 expression." (PMID 38164270, 2024). "After binding with its ligand IL15, IL15RA expressed by malignant tumor cells presents it to NK and T cells, activating effector cells and further attacking malignant tumor cells [28‒31]." (PMID 39396119, 2024). "In this review, an overview of the current understanding of ILC1s in cancer is provided, together with the main ILC1-activating cytokines IL-12 and IL-15 in the context of ongoing clinical trials." (PMID 38745765, 2024). "Combining IL-15 with anti-CTLA-4 and anti-PD-L1 antibodies demonstrated highly effective antitumor effects in several cancer models." (PMID 39507777, 2024). "The relationship between IL2 and IL15 has been demonstrated, including cancer therapy, as well as the relationship between IL2 and IL17A, and between IL15 and IL17A." (PMID 37691946, 2023). "With the emergence of cytokine therapy for cancer, the four cytokines of the common cytokine receptor γ chain (γc, CD132) family, containing interleukin-2 (IL-2), IL-7, IL-15, and IL-21 are dictated to regulate the T cell stemness formation and maintenance." (PMID 38049832, 2023). "Cancer cells seriously invaded both lung and liver in PBS and DC vesicle groups, and IL-15 indicated a weak metastasis-inhibitory ability." (PMID 37875481, 2023). "In summary, these results showed that both α.anti-NKG2A.IL-15 and β.anti-NKG2A.IL-15 have a strong potency on increasing cytotoxic activity of NK and CD8+ T cells against resistant cancer cells." (PMID 37936122, 2023). "Similar approaches have been applied to IL-15/IL15R and IL-7/IL-7R expressing systems in cancer therapy." (PMID 37237491, 2023). "Several preclinical models and clinical trials demonstrated the ability of IL-15 to counteract HCC-induced NK dysfunction, and these findings make it a promising cytokine for cancer immunotherapy." (PMID 37686245, 2023). "Another study showed that IL-15-incorporated NKCE (161533 TriKE/GTB-3550) rectified the functional defects of NK cells and extended the survival of cancer patients post-hematopoietic stem cell transplantation." (PMID 37638058, 2023). "Analysis of the secreted protein profiling of progressive cancers showed little amounts of NK cell-stimulating molecules such as IFN and IL-15." (PMID 37190251, 2023). "An evolution of TriKE format is TetraKE, which has been described to simultaneously engage EpCAM and CD133 for targeting carcinoma cells and cancer stem cells, along with a CD16-engaging moiety and IL-15 for NK cell expansion." (PMID 36793863, 2023). "We found tofacitinib suppressed IL-15-mediated JAK/STAT pathway stimulation, cytotoxicity to cancer cells and iNeurons, granzyme B and perforin expression, and cytokine expression in the NK-92 cell line." (PMID 35197969, 2022).
cancer (continued). "Treatment of NK cells in culture with interleukins 2, 12, or 15 (IL-2, IL-12, IL-15) and interferon-α (IFN-α) can increase their cytotoxicity towards cancer cells and even toward cancer lines that are generally resistant to NK cell killing." (PMID 35326467, 2022). "Conversely, IL-15 from other sources, including dendritic, stromal, and endothelial cells, did not seem to affect intratumoral g1 ILCs, strongly suggesting that IL-15 trans-presentation by cancer cells might contribute to directly activating ILC1ls and promoting their phenotype." (PMID 36372017, 2022). "The safety and efficacy of α-PD-1/PD-L1 combined with IL-2 pathway agonist (NKTR-214/BEMPEG), PEGylated IL-10 (Pegilodecakin), IL-12 plasmid (Tavo), IL-15 agonist (ALT-803), or PEGylated IFN-α had been validated in cancer patients." (PMID 35062949, 2022). "In contrast, IL-15 targets primarily CD8+ T cells and NK cells, and thus high doses are used for cancer therapy." (PMID 36429085, 2022). "Furthermore, studies have reported that if IL-15 deficiency leads to a range of problems, suggesting that these variants may not affect the functional profile of IL-15 in cancer." (PMID 36467072, 2022). "However, the roles of IL-15 in other types of cancer remain unknown." (PMID 36467072, 2022). "Several current products include ALT-803 ALT-803, P22339, chimeric IL-15 apolipoprotein A-I, or NKTR-255, illustrating the promise of IL-15 in cancer therapy." (PMID 36467072, 2022). "The ability of IL-15 that is trans-presented by IL-15Rα to activate NK cells and CD8+ T cells has generated a lot of interest in exploiting it for cancer immunotherapy." (PMID 34956227, 2021). "Although it was already known that DC trans-presentation of IL-15 was required for NK cell priming in sterile inflammation, the possibility to trigger this pathway by immune-modulating agents in the context of primary cancer may represent an innovative approach for cancer immunotherapies." (PMID 34203391, 2021). "These IL-15 superagonists exhibited an augmented antitumor effect compared to the IL-15 monomer in multiple studies, which pushed them (mostly ALT-803) into clinical trials to test their efficacy and safety in cancer treatment." (PMID 34107983, 2021). "The potential of IL-15 to reactivate the memory CD8+ T cells during the infectious challenge proves its adjuvanticity in vaccine development and cancer immunotherapy." (PMID 33953717, 2021). "For instance, in vivo activation of NK cells using cytokine treatments (e.g., IL2, IL12, IL15, IL18 and IL21) has been investigated in several types of mouse cancer models and human cancers." (PMID 35008348, 2021). "The expression of CDH6, DPYSLE3, GJA1, IL15, and ACTA2 is also relevant to survival in many types of cancers, but its mechanism of action in CRC requires further study to explore its impact." (PMID 34211976, 2021). "An IL-15 superagonist – IL-15 peptide fused with the alpha subunit of its receptor, IL15-Rα – is a promising immunotherapeutic agent for cancer treatment." (PMID 33679747, 2021). "T cells were co-cultured with cancer spheroids for 48 h in OP9 medium supplemented with 5 ng/ml IL-7 and 5 ng/ml IL-15." (PMID 34099861, 2021). "The data we presented here support a future clinical trial of IL‐15 combined with a CD40 agonist for PDAC, since we showed for the first time that this combination holds great potential for improved cancer treatment outcome." (PMID 32821382, 2020). "NeoleukinTM-2/15 cancer treatments have also been shown to increase the CD8+: Treg suggesting a mechanism similar to IL2 and IL15." (PMID 33216834, 2020). "In recent phase I and II trials, iC9/CAR-CD19/IL-15 NK cells were prepared ex vivo and infused into patients with relapsed or refractory CD19-positive cancers after lymphodepleting chemotherapy." (PMID 32762681, 2020).
cancer (continued). "The effect of IL-15 administration combined with checkpoint inhibitors (anti-CTLA-4 and/or anti-PD-1 mAbs) is currently under investigation in patients with cancers refractory to other therapies." (PMID 32010130, 2019). "Cancer accounts for only 3.3% of total diseases related to selected myokines (apelin, BDNF, IL-15, irisin, SPARC), but additional myokines have been shown to be more clearly involved in cancer cachexia." (PMID 30984014, 2019). "The remaining CD5-depleted cells were then exposed to human IL-2, IL-15, IL-2/IL-15 combination or the feeder cell line EL08-1D2, which is derived from murine embryonic liver cells, instead of human cancer cells, like the K562 line." (PMID 31717876, 2019). "Multiple cytokines such as interleukin-15 (IL-15) and IL-12 have been recruited to empower CAR T cell therapy against the cancer cells." (PMID 30108584, 2018). "IL-15 promotes the effector functions of both CD8+ T cells and natural killer (NK) cells and thus plays a pivotal role in cancer immunosurveillance." (PMID 29141914, 2018). "The IL-15 superagonist complex with IL-15Rα, named ALT-803, is being actively tested in the clinic for the treatment of cancer." (PMID 30072983, 2018). "Nektar Therapeutics has developed a polymer-conjugated human IL-15 (NKTR-255) that exhibits a prolonged in vivo half-life and enhanced potency, which is currently being examined as a potential cancer immunotherapeutic agent." (PMID 30400822, 2018). "These respective cancer cell lines were co-cultured with PBMCs and 1615EpCAM133, NCI derived IL-15, 16133 or EpCAM16." (PMID 27650544, 2016). "The original contribution of this work is a self-sustaining TetraKE comprising an anti-CD16 scFv for NK cell engagement, anti-EpCAM scFv for carcinoma recognition, anti-CD133 scFv for CSC recognition, and an IL-15 cross-linker to sustain the NK cell response." (PMID 27650544, 2016). "As for the use of OK432 in cancer immunotherapy, we have demonstrated that OK432 is better than the cytokine cocktail in several critical aspects, i.e. IL-12p70 and IL-15 production, CD40 expression and T-cell stimulation." (PMID 21208424, 2011). "Using serial imaging, we tracked cancer population growth over time in mono and coculture conditions across a six-point gradient of IL-15 concentration and with or without ribociclib treatment." (PMID 40032842, 2025). "An earlier study using a rat model of cancer cachexia indicated that IL‐15 reduces the rate of protein degradation without impacting protein synthesis." (PMID 39764565, 2025). "This led to increased NK cell-mediated cytotoxicity and greater NK cell expansion compared to the BiKE lacking IL-15 in a host of cancer cell lines: colorectal cancer, Burkitt lymphoma, and promyelocytic leukemia cell lines." (PMID 39294470, 2024). "Administration of AII in the vicinity of cancer cells in patients might be problematic, but our data suggests that this may in part be circumvented by co-administration of cytokines such as IL2 or IL15." (PMID 38184565, 2024). "Moreover, to potentiate anti-cancer immunity, some OVs have been genetically engineered to express different cytokines (GM-CSF, IL12, and IL15), to enhance antigen presentation, or to elicit a more effective immune response against cancer cells." (PMID 38473776, 2024). "Bulk and single-cell RNA-seq data were collected and analyzed from multiple studies and cancer types, and results showed that a single IFN-α/β/IFN-γ/IL-15 pathway could predict clinical responses and survival to ICB." (PMID 38758367, 2024). "Clinical trials have demonstrated that IL-15 can significantly improve the persistence and effectiveness of CAR NK cells in targeting CD19-positive lymphoid tumors, offering new hope for patients with certain types of cancer." (PMID 39335671, 2024). "Conversely, CXCL16 and IL-15 expressing CCR7+ DCs may recruit and sustain CXCR6+ cytotoxic T cells crucial in cancer immunosurveillance." (PMID 38267413, 2024).
cancer (continued). "Trispecific (CD16, IL-15, CD133) and tetraspecific (CD16, IL-15, EpCAM, CD133) NK cell engagers have also demonstrated appreciable anti-cancer efficacy against colorectal Caco-2 cells, as well as a panel of breast, prostate, HNSCC, CRC, and AML cell lines, respectively." (PMID 38612911, 2024). "To date, FT596, a muti-targeting CAR-NK cell which possesses anti-CD19 CAR, non-cleavable CD16 receptor, and IL15/IL-15α was developed to enhance cancer-killing ability and improve the persistence of CAR-NK cells." (PMID 38726000, 2024). "It is encouraging that the use of recombinant IL-15 and the supergonist ALT-803 (N-803) has been well tolerated in cancer trials, which may bode well for their use in future NS trials." (PMID 38672094, 2024). "Most cancer-related studies on IL7 and IL15 have focused on hematological malignancies." (PMID 38055067, 2023). "In addition, the downregulation of IL-15 and CXCL10 in cancer cells from TLS-low tumors was also observed in an independent single-cell RNA-sequencing dataset." (PMID 37348499, 2023). "Furthermore, during infection and cancer, A2AR engagement seems to inhibit via IL-15 signaling blockade, the generation of human CD39+NK cells endowed with a potent degranulation capacity and overexpression of IFNγ and TNFα." (PMID 37753093, 2023). "Although the remarkable antitumor efficacy of IL12 has yet to be replicated in preclinical human models, preclinical studies on the combination of IL12, IL15, and IL18 might represent ideal approaches to generating NK and DCs for cancer therapy." (PMID 36968220, 2023). "IL-15 is a cytokine necessary for the function and homeostasis of CD8+ T cells, NK and NKT cells, and it has been proposed as a novel immunomodulatory treatment for several diseases such as cancer and HIV infection." (PMID 36767310, 2023). "Furthermore, IL-12, IL-15, and IL-18 induced CD25 and CD137 upregulation on CIML NK cells even after incubation with cancer cell lines (K562, HepG2, and SK-Hep-1 cells) after a 6-day interval." (PMID 36932395, 2023). "More than 170 clinical trials using different IL-15 agents for cancer treatment have been initiated worldwide, but no IL-15 agonist drug/therapy has been approved for marketing so far." (PMID 37251333, 2023). "A significant expression difference of IL-15 was evaluated in 33 types of cancer in paired or unpaired samples except those without normal tissue data." (PMID 36467072, 2022). "Cancers with decreased IL-15 expression correlate with decreased patient survival, which led to the development of IL-15 superagonists and NK cell modifications that can overcome TGF-β-mediated inhibition of the IL-15 pathway." (PMID 35874677, 2022). "Our results show that the interleukin 15 pathway appeared to increase in activity in SSTR2-high groups in 92.31% of cancers, and the interleukin 2 pathway appeared to increase in activity in SSTR2-high groups in 96.15% of cancers." (PMID 35264912, 2022). "However, our allogeneic mACE2-CAR_sIL15 NK cells express IL-15, which can sustain NK cell survival in treated patients infected by SARS-COV-2, as demonstrated in cancer patients." (PMID 35546150, 2022). "Further, we analyzed the expression of LIPT14 in pan-cancer, and we found that LIPT1 and IL-15 had a strong and significant positive correlation in SKCM and READ, and a general level of positive correlation in LUAD, ESCA, PCPG (p less than 0.05), but not with UCS, COAD." (PMID 36467072, 2022). "In addition, IL-15 is positively correlated with ferroptosis/cuproptosis-related genes (ACSL4 and LIPT1) in pan-cancer." (PMID 36467072, 2022). "Novel IL-15-based therapies have combined it in preclinical studies with other immunotherapeutic agents, such as monoclonal antibodies (rituximab, alemtuzumab), CD40 agents, cancer vaccines, and other cytokines (IL-12, IL-18, and IL-21)." (PMID 35529882, 2022).